INS (insulin)
Diseases named in the same sentence as INS in open-access papers (continued):
Sharing a sentence is not in itself a finding about the gene and the disease.
Insulin resistance (continued). "A significant association has been demonstrated between TyG levels and the Homeostatic Model Assessment of Insulin Resistance (HOMA-IR) and high insulin-normal glucose clamp test, with the TyG index potentially outperforming the HOMA-IR in predicting certain diseases." (PMID 40895101, 2025). "Skeletal muscle insulin resistance, a hallmark of T2DM, caused by a reduced response to insulin, impairs glucose uptake and disrupts the maintenance of normal glucose levels after food intake." (PMID 40894926, 2025). "Although most adults with obesity are insulin resistant for glucose uptake, some remain relatively insulin sensitive, and factors helping to protect against the development of insulin resistance in these individuals are not clear." (PMID 39487600, 2025). "Whilst not currently included as a MetS trait characterising MASLD, we were not able to explore the impact of insulin resistance on the risk of CKD since fasted glucose and insulin concentrations are not available within the UK BioBank cohort." (PMID 39548715, 2025). "With worsening insulin resistance, the pancreas must increase insulin secretion to sustain normal blood glucose levels." (PMID 40260393, 2025). "Given that HDAC inhibitors have the capacity to ameliorate insulin resistance, we propose that these inhibitors may mitigate the progression of T2DM-CRC co-morbidity by enhancing insulin sensitivity." (PMID 39901036, 2025). "The homeostasis model assessment of insulin resistance (HOMA-IR) is one of the most widely used indicators in clinical practice, yet it remains inaccessible in many primary hospitals due to the inability to measure insulin levels." (PMID 41377946, 2025). "Enhanced SCFAs production may improve fasting insulin levels and HOMA-IR, thereby reducing insulin resistance." (PMID 41154691, 2025). "Decreased insulin signaling in adipocytes could potentially trigger the breakdown of fats, leading to the release of NEFA, which could then worsen insulin resistance." (PMID 40786169, 2025). "Unlike fg-SRLs, PAS results in a significant decrease in insulin levels without improvement in insulin resistance." (PMID 39859181, 2025). "Prolonged exposure to elevated levels of circulating insulin leads to the development of insulin resistance in peripheral tissues, and over time, the pancreas fails to produce sufficient insulin to overcome this cellular resistance." (PMID 40070584, 2025). "Collectively, these metabolic alterations may sustain insulin resistance in chronic SCI, even in the presence of normal glycemic indices, reflecting a disconnect between glucose appearance and insulin effectiveness." (PMID 40363903, 2025). "Unlike type 1 diabetes, T2D is characterized by insulin resistance and/or dysfunction of pancreatic β-cells, leading to sustained high blood sugar levels and the former is due to autoimmune destruction of insulin-producing cells." (PMID 39944639, 2025). "It is not yet very clear whether BCAAs are a causative factor of insulin resistance or a biomarker of impaired insulin action, although there is clear evidence that elevated BCAA concentrations predict future insulin resistance." (PMID 40806262, 2025). "Insulin resistance is a condition, common in obesity and type 2 diabetes, where the body’s cells do not respond properly to insulin, a hormone that controls blood sugar." (PMID 41002547, 2025). "In recent years, more and more research interest has been focused on insulin signaling and insulin resistance in the CNS, not least their role in cognition." (PMID 39876043, 2025). "This microenvironment promotes the secretion of cytokines, such as TNF-α and IL-6, which impair insulin signaling by inhibiting the IRS-1/PI3K/Akt pathway, contributing substantially to the systemic insulin resistance observed in the Ob-Veh and HE-Ob-Veh groups." (PMID 41471698, 2025).
Insulin resistance (continued). "The metabolic score for insulin resistance (METS-IR) is a tool for evaluating IR without direct insulin measurement, demonstrating potential across many metabolic disorders." (PMID 41261678, 2025). "In contrast, other research found that kefir can notably reduce fasting insulin levels and insulin resistance (HOMA-IR) without impacting FBS or HbA1c levels." (PMID 40565686, 2025). "In hyperinsulinemia, the body does not respond properly to the production of insulin from the pancreas, and it develops insulin resistance." (PMID 39857716, 2025). "When insulin resistance increases, insulin production is no longer adequate, potentially leading to type 2 diabetes mellitus (T2DM)." (PMID 40109401, 2025). "Because insulin resistance is correlated with MASLD progression, we asked whether Tbx3-KO mice were protected from MASLD through altered insulin sensitivity." (PMID 40638249, 2025). "We found that in utero exposure to maternal hyperglycaemia in the absence of maternal obesity and insulin resistance affected glucose regulation and insulin sensitivity in offspring during early adulthood, despite consumption of a healthy diet since weaning." (PMID 40021748, 2025). "Hepatic dysfunction of the denitrosylase GSNOR elevates S-nitrosylation of lysosomal enzymes, disrupts autophagic flux, and promotes insulin resistance in obesity, whereas restoring GSNOR activity or expressing nitrosylation-resistant lysosomal proteins rescues autophagy and improves insulin action." (PMID 41373704, 2025). "The kinome analysis of T2D iHeps also predicted the kinases responsible for emergent signaling that may act as drivers of insulin resistance, including ROCK1/2, BCKDK, and MST4 for insulin-regulated phosphorylations." (PMID 40231468, 2025). "Grifola frondosa polysaccharides induced significant glucose consumption in insulin-resistant HepG2 cells after 24 h of treatments compared to non-treated controls, suggesting improved insulin resistance." (PMID 39859540, 2025). "Fifth, there was an absence of insulin level measurements, which prevented direct evaluation of the relationship between insulin resistance and the TyG index." (PMID 40572675, 2025). "Additionally, it may impair insulin-stimulated glucose uptake and glycogen synthesis in skeletal muscle and adipocytes in vivo by blocking the translocation of glucose transporter protein-4, resulting in insulin resistance, affecting the development of gestational diabetes." (PMID 41573549, 2025). "The homeostatic model assessment for insulin resistance (HOMA-IR) index was calculated according to the fasting blood glucose (FBG) and FINS, revealing that hesperetin enhanced metformin’s effect on insulin sensitivity in rats with DM." (PMID 40076550, 2025). "In this study, while insulin levels were not significantly different from the control in all experimental groups, blood glucose levels were notably higher in the insulin resistance (ID) group compared to all other groups." (PMID 39906623, 2025). "We found that hesperidin supplementation significantly reduced the homeostatic model assessment of insulin resistance (HOMA-IR) (WMD: −0.43, 95%CI: −0.82, −0.03; p = 0.034) and increased the quantitative insulin sensitivity check index (WMD: 0.05, 95%CI: 0.01, 0.08; p = 0.005)." (PMID 41586243, 2025). "While not examined here, perhaps whole‐body insulin resistance applies to PBMCs as well, and due to a reduced insulin‐stimulated glucose uptake, these immune cells shift their metabolism towards mitochondrial oxidative phosphorylation." (PMID 40525760, 2025). "Insulin resistance is the precursor of type 2 diabetes, a condition in which cells in the body do not react appropriately to insulin." (PMID 41155022, 2025). "Markers of insulin resistance, such as insulin level and HOMA-IR, were higher in patients without stainable iron." (PMID 41264906, 2025).
Insulin resistance (continued). "Ginger also significantly lowered fasting plasma glucose, glycated hemoglobin (HbA1c), insulin, CRP, and the homeostatic model assessment of insulin resistance (HOMA-IR) index compared to the placebo group in patients with DM2, a common comorbidity in individuals with obesity." (PMID 40733199, 2025). "Consequently, individuals diagnosed with LADA may not require insulin earlier, exhibiting a wide range of phenotypes, from the presence of insulin resistance to insulin deficiency resulting from beta-cell destruction, which falls somewhere between T1DM and T2DM." (PMID 41024896, 2025). "Other tests used to assess glucose intolerance include homeostasis model assessment of insulin resistance (HOMA-IR), homeostasis model assessment of beta-cell function (HOMA-β), quantitative insulin sensitivity check index (QUICKI) and fasting glucose-to-insulin ratio (G/I ratio)." (PMID 40094911, 2025). "Third, we did not assess the homeostasis model assessment of insulin resistance or compare it with the TyG–BMI because of insufficient data on insulin levels during follow-up." (PMID 40909885, 2025). "Fourth, there was no information on hemoglobin A1c and insulin which were crucial determinants to evaluate insulin resistance severity." (PMID 39806968, 2025). "Additionally, these results align with prior reports showing that prolonged high-fat feeding alone can induce insulin resistance, and that low-dose STZ effectively accelerates this transition toward a more pronounced insulin-resistant and diabetic phenotype." (PMID 41002949, 2025). "Insulin resistance, a condition in which the body does not utilize insulin as it should, and decreased insulin production are the two primary symptoms of T2DM." (PMID 40831865, 2025). "Not all patients with MetS exhibit insulin resistance, but when it is present, insulin insensitivity enhances lipolysis, leading to increased fatty acid flux to the liver." (PMID 40723828, 2025). "Some endocrine disruptors can directly induce insulin resistance and impair insulin production and secretion without significantly impacting body weight." (PMID 39775248, 2025). "This suggests that the post-surgical microbiota independently influences blood glucose levels by altering the gut morphology and reducing Sglt1-mediated glucose absorption, regardless of changes in BMI, insulin, or insulin resistance." (PMID 40869254, 2025). "Additionally, tranilast improved glucose clearance and insulin sensitivity in HFHC diet-fed mice, as evidenced by enhanced glucose tolerance and reduced insulin resistance." (PMID 39755206, 2025). "Third, serum insulin levels and insulin resistance indices (e.g., HOMA-IR) were not directly measured." (PMID 40870712, 2025). "Insulin resistance (IR) is a hazard to human health in which peripheral insulin-target organs, like the liver, become less sensitive to normal levels of insulin." (PMID 40406487, 2025). "To summarize, impaired insulin-mediated suppression of plasma glycerol and NEFA levels during euglycemic–hyperinsulinemic clamps indicated higher rates of lipolysis and suggested adipose tissue insulin resistance in T1D." (PMID 39998445, 2025). "In our studied population, reduced insulin sensitivity relates to a higher prevalence of attenuated executive function even among participants with HOMA‐IR values below the 75th percentile threshold, indicating a low level of insulin resistance." (PMID 40302139, 2025). "Post-PTx showed the following: lower glycaemia, fasting insulin, insulin resistance (HOMA-IR) improvement, and reduced rate (but not all studies agreed)." (PMID 40283231, 2025). "In the ART cohort, the mRNA expression level of SREBP‐1 exhibited a positive correlation with BMI, ApoB, fasting blood glucose, fasting insulin, and the insulin resistance index, whereas it demonstrated a negative correlation with ApoA1." (PMID 41323197, 2025).
Insulin resistance (continued). "Evidence on the relationship between no-insulin-based insulin resistance (IR) surrogates and the prevalence of coronary heart disease (CHD) in remains limited." (PMID 41458555, 2025). "The traditional classification of DM is mainly based on abnormalities in insulin secretion and action, such as type 1 DM due to an absolute lack of insulin secretion and T2DM due to insulin resistance and relative insulin deficiency." (PMID 40778306, 2025). "Moreover, elevated glucose and insulin levels observed in the WSM group align with research, which identifies insulin resistance as a fundamental component of metabolic syndrome." (PMID 40630388, 2025). "Previous studies have shown that insulin resistance arises when insulin secretion increases but fails to adequately reduce blood glucose levels, thus elevating the risk of T2DM." (PMID 41003141, 2025). "The LP-IR change observed in our trial suggests that pecan intake affected early insulin resistance, without impacting glycemic outcomes including hemoglobin A1c, fasting insulin, or glucose." (PMID 40113170, 2025). "Biomarkers of insulin resistance (fasting serum insulin and serum glucose): The mean changes from baseline to 2 weeks of fasting glucose and insulin were not significant for any dosage." (PMID 39715964, 2025). "Adolescents, especially those with type 1 diabetes mellitus, frequently experience increased insulin demands, reflecting a temporary state of insulin resistance even in the absence of obesity." (PMID 39941454, 2025). "Similarly, the Homeostatic Model Assessment of Insulin Resistance (HOMA-IR) and Quantitative Insulin Sensitivity Check Index (QUICKI) are commonly used in clinical settings." (PMID 40093882, 2025). "Compromised MAM integrity may impair insulin signaling pathways (including Akt/PKB activation) and disrupt glucose/lipid homeostasis, ultimately contributing to hepatic insulin resistance (IR)." (PMID 40918255, 2025). "Our data demonstrated that rats fed SPs for 4 wk on a 3-h-restricted schedule already showed insulin hypersecretion, whereas by 9 wk, rats fed SPs had developed insulin resistance without their GTTs showing a diabetic pattern." (PMID 40074175, 2025). "For example, insulin and HOMA-IR likely have high RC values on the insulin resistance factor." (PMID 41220482, 2025). "In this study, women with insulin resistance had significantly higher fasting glucose and insulin levels compared to the non-insulin-resistant group (mean, 104.66 mg/dL vs. 88.90 mg/dL and 18.76 μIU/mL vs. 8.27 μIU/mL; p < 0.001)." (PMID 40137151, 2025). "This diet reduced hepatic insulin resistance and normalized basal rates of hepatic glucose production by decreasing gluconeogenesis, and these changes occurred independent of any change in insulin-stimulated peripheral glucose metabolism." (PMID 41009753, 2025). "Insulin resistance (IR) is a condition in which the body’s cells do not respond adequately to insulin, a hormone crucial for glucose metabolism." (PMID 40289929, 2025). "In particular, the insulin level at 60 min was recorded as 38.60 ± 26.25 μU/mL in the group with insulin resistance, in contrast to 21.34 ± 15.96 μU/mL in the group without resistance." (PMID 41300682, 2025). "Investigators have frequently used either the absence of the metabolic syndrome or insulin resistance (usually calculated by fasting insulin and glucose levels based on several models) to define metabolic health." (PMID 39679900, 2025). "The pathogenetic mechanisms of insulin resistance in PA are not entirely clarified yet; however, it seems that aldosterone exerts a role on insulin‐target tissues through genomic and non‐genomic effects via MR and glucocorticoid receptor (GR)." (PMID 40079488, 2025). "One patient in the ALEM group reverted to insulin treatment, attributed to insulin resistance (C-peptide > 1800 pmol/L) rather than pancreas graft dysfunction." (PMID 40594479, 2025).
Insulin resistance (continued). "Insulin resistance occurs when body tissues do not respond effectively to insulin, necessitating increased insulin production." (PMID 40357783, 2025). "The offspring of AD mice bred with insulin resistant mice exhibited cognitive impairment at an earlier age than AD mice lacking insulin resistance." (PMID 41282256, 2025). "Insulin resistance is a pathophysiological condition in which organs do not respond appropriately to insulin, observed in GDM pregnancies, post-GDM women, and GDM offspring, and the GDM umbilical–placental circulation." (PMID 40453589, 2025). "We reported in previous study that increased TRB3 in skeletal muscle under stress conditions, including ER stress and HFD, impairs insulin-stimulated Akt phosphorylation and whole-body metabolism, and that TRB3 knockout abolishes the development of HFD-induced insulin resistance." (PMID 40791468, 2025). "After taking 1,000 mg of ω-3 fatty acids daily for 6 weeks, GDM patients’ insulin resistance also improved, but their blood glucose, insulin sensitivity and blood lipids did not change." (PMID 39963668, 2025). "Research has shown that excessive levels of GPX1 in mouse models can lead to insulin resistance and hyperinsulinemia, primarily due to the inhibition of normal insulin‐mediated Akt signaling." (PMID 40599237, 2025). "The following are several possible mechanisms we have considered: Insulin resistance leads to elevated insulin levels through a negative feedback mechanism, thus resulting in hyperinsulinemia." (PMID 39933012, 2025). "Our pharmacology results will also have to be assessed in female obese mice, but generally the male obese C57BL/6 mouse better captures common obesity in humans with concomitant insulin resistance, whereas female C57BL/6 mice are more resistant to DIO and often remain insulin sensitive throughout." (PMID 40787810, 2025). "Although our model does not represent a typical diabetic pregnancy, lacking spontaneous insulin resistance, as observed for gestational diabetes, and without insulin replacement, as observed for DM1, it is based on a chemically induced beta cell destruction." (PMID 40563978, 2025). "Simultaneously, ROS disrupts insulin signaling in peripheral tissues by promoting IRS-1 serine phosphorylation and degrading phosphatidylinositol-3-kinase (PI3K)/Akt activation, leading to insulin resistance." (PMID 40492113, 2025). "Indeed, mouse primary hepatocyte that were pre-treated overnight with MEV had decreased Akt phosphorylation following stimulation with insulin, highlighting that MEV can directly induce insulin resistance." (PMID 40484172, 2025). "The mechanisms for the reduction of insulin dose in the absence of change in insulin resistance is of interest." (PMID 41285865, 2025). "Although the homeostasis model assessment of insulin resistance (HOMA-IR) is widely used to estimate insulin resistance in clinical and research settings, its application is limited by the need for fasting insulin measurements and relatively complex procedures." (PMID 40964523, 2025). "A key feature of MetS is insulin resistance (IR), which occurs when cells do not respond adequately to insulin, a hormone produced by the pancreas that regulates blood sugar levels." (PMID 39776279, 2025). "ARBs mitigate insulin resistance by inhibiting the RAAS, leading to decreased cytokine production (including tumor necrosis factor-α), elevated adiponectin levels, and enhanced pancreatic insulin secretion and cellular insulin signaling." (PMID 41488134, 2025). "Furthermore, mice transplanted with fecal microbiota from individuals with PCOS exhibited increased insulin resistance compared to those subjected to FMT from healthy donors, as evidenced by glucose tolerance tests (GTTs) and insulin tolerance tests (ITTs)." (PMID 41082373, 2025).